LYZ (lysozyme)
Diseases named in the same sentence as LYZ in open-access papers (continued):
Sharing a sentence is not in itself a finding about the gene and the disease.
Crohn disease (13 papers, 2019 to 2025). A gastrointestinal disorder characterized by chronic inflammation involving all layers of the intestinal wall, noncaseating granulomas affecting the intestinal wall and regional lymph nodes, and transmural fibrosis. "LRRK2 has previously been implicated in Crohn’s disease through its expression in intestinal epithelial cells, specifically in Paneth cells, where it was shown to be required for anti-microbial peptide lysozyme secretion." (PMID 40394349, 2025). "In both patients with Crohn’s disease and the TNFΔARE mouse model of chronic ileitis, severity of inflammation has been correlated with loss of LYZ+ Paneth cells." (PMID 38068838, 2023). "LYZ messenger RNA was significantly up-regulated in the colon epithelial cells of patients with ulcerative colitis and Crohn’s disease." (PMID 40416362, 2025). "For example, Atg16l1 T300A mice mimic human Crohn’s disease features, with fewer secretory granules and disorganized lysozyme." (PMID 40564109, 2025). "Reportedly, an augmented serum lysozyme level was found in patients with Crohn’s disease and ulcerative colitis." (PMID 36678320, 2023). "Norovirus infected mice with reduced ATG16L1 expression have decreased and disorganized Paneth cell granules and decreased lysozyme, and similar defects have been identified in Crohn’s disease patients." (PMID 32671059, 2020). "Increased Paneth cell death has been identified in the ileum of Crohn’s disease patients, and treatment of control patient biopsies with TNF has been shown to reduce Paneth cell-associated lysozyme mRNA, which can be rescued by Nec-1, a RIP1 inhibitor." (PMID 32671059, 2020). "In mice expressing a Crohn’s disease-associated risk polymorphism (ATG16L1T300A), secreted lysozyme is significantly decreased, suggesting that the dysfunction of the ER stress response and ATG16L1-dependent secretory macroautophagy etiologically are associated with Crohn’s disease." (PMID 37762105, 2023).
dry eye (13 papers, 2012 to 2024). "The loss of lysozyme’s protective function on the ocular surface may further exacerbate dry eye symptoms and contribute to the overall instability of the tear film." (PMID 39408709, 2024). "Interestingly, this downregulation of proteins with antibacterial activity like lysozyme and lactotransferrin may be related to the increased risk of infectious diseases of the ocular surface in dry eye patients." (PMID 33372592, 2020). "Among these dry eye biomarkers, lactoferrin and lysozyme have been considered the more accepted ones since a decrease in lactoferrin and lysozyme and an increase in albumin are related to an early inflammatory response in dry eye disease." (PMID 36830827, 2023). "Tear film lysozyme and lactoferrin can be considered as simple, non-invasive, and economical biomarkers for diagnosing dry eye." (PMID 36547340, 2022). "The study of dry eye syndrome in human found the primary proteins such as lysozyme, lactoferrin, and lipocalin was reduced but serum-derived proteins, such as serum albumin, IgG, and ceruloplasmin, were increased." (PMID 34316222, 2021). "A low level of tear lysozyme implies a reduced bacteriostatic effect of the tears.This could explain why patients with dry eye disease and Sjögren’s syndromeare more prone to ocular surface infections than those with dry eyes caused by analteration of the meibomian glands." (PMID 34431892, 2021). "The tear lysozyme was used as one of the potential biomarkers for diagnosis of human dry eye and mucosal immune competence." (PMID 34316222, 2021). "Researchers also found the single protein lysozyme test to be insufficient for the diagnosis of dry eye." (PMID 26605353, 2014). "Lysozyme is probably the earliest tear protein studied in conjunction with dry eye, and the level of tear lysozyme was noted to increase with age till 40 and decrease thereafter." (PMID 26605353, 2014). "Normal production of tear proteins, such as lysozyme, lactoferrin, lipocalin, and phospholipase A2 beta-2 microglobulin, is reportedly decreased in keratoconjunctivitis sicca." (PMID 23272196, 2012). "The lysozyme and lactoferrin levels are significantly decreased in dry eye patients." (PMID 36547340, 2022). "Similarly, a human study reported the amount of lysozyme in human tears also decreased in early dry eye." (PMID 34316222, 2021). "Additionally, LYZ has also shown to be down-regulated in patients with dry-eye syndrome." (PMID 28419103, 2017). "Nevertheless, lysozyme levels may be useful in specific contexts, for example, to check for adverse effects of beta-adrenergic receptor blocking drugs such as Practalol, which reduced tear lysozyme levels or to detect dry eye from specific occupational exposures in coal mining." (PMID 26605353, 2014). "In conclusion, reduced tear lysozyme concentration showed an excellent diagnosticperformance in distinguishing patients affected by Sjögren ́s syndrome fromthose with non-dry-eye or MGD dry eye." (PMID 34431892, 2021).
adenoma (12 papers, 2017 to 2025). A neoplasm arising from the epithelium. "As expected, nuclear β-catenin detection was higher in carcinomas than in adenomas but we detected a significant correlation between the presence of nuclear β-catenin and LYZ positivity in the adenoma samples." (PMID 34831152, 2021). "Remarkably, adenoma glands enriched in LYZ-positive Paneth cells displayed higher ICN1 levels (yellow arrowheads) when compared with the adjacent LYZ-negative glands of the same tumor area (blue arrowheads)." (PMID 34831152, 2021). "Gene expression of Defa and Lyz1 confirmed the depletion of PC-lineage cells in small intestinal adenomas, which was consistent with the findings for lysozyme immunofluorescence staining." (PMID 33372038, 2021). "Our results indicate that Paneth cell detection and LYZ expression is correlated with Wnt/β-catenin and Notch activation specifically in low-grade adenoma samples." (PMID 34831152, 2021). "Using this approach, we found lysozyme-positive cells in adenomas of ApcMin mice, particularly in the small intestine, and the same was true of human small intestinal and colonic adenomas." (PMID 33372038, 2021). "We detected LYZ-positive cells (considering positive samples classified as ++ and +++) in about 40% of the adenoma samples, covering different areas of the tumor tissue." (PMID 34831152, 2021). "As expected, adenomas from PCdel mice displayed low expression of PC marker genes, such as members of the Defensin family (Defa21 and Defa22) and lysozyme itself (Lyz1)." (PMID 33372038, 2021). "The number of lysozyme+ Paneth cells was also significantly increased in ApcminSh3bp4 cKO adenomas compared to the control Apcmin littermates." (PMID 30811977, 2019). "Some of these cells were positive for lysozyme, making it unclear whether they were dislocated Paneth cells or cells that had arisen within the adenoma." (PMID 40221753, 2025). "Moreover, we stained 14 early adenomas (5 from FAP patients) for neoplastic Lysozyme+ IDO1+ Paneth cells." (PMID 32444775, 2020). "Lysozyme+ and Lysozyme+ IDO1+ Paneth cells were found in ten adenomas (four from FAP patients) and six adenomas (three from FAP patients), respectively." (PMID 32444775, 2020). "Immunohistochemistry (IHC) revealed 2 × 3 more lysozyme-positive cells in DKO adenoma vs ApcMin control sections, confirming that the former contain more Paneth cells than adenomas with functional Bcl9 or Pygo." (PMID 30760710, 2019). "Using this approach, cells with these staining characteristics were recognized in small intestinal adenomas of ApcMin mice; however, unlike the normal epithelium, lysozyme-positive cells in these adenomas were not always lectin positive (bottom row)." (PMID 33372038, 2021). "Indeed, lysozyme and other Paneth cell markers behaved similarly, showing a tendency to be upregulated in both types of DKO vs control adenomas." (PMID 30760710, 2019). "Of note, although cells expressing the PC marker lysozyme (LYZ1) were notable in Lgr5-derived tumors (Lgr5/Apc: 30.0% ± 18.5% positive tumor cells), they were almost absent in adenomas that originated from PCs (Lyz1/Apc: 0.48% ± 1.16%)." (PMID 38902475, 2024). "Notably, LYZ-positive tumors displayed a robust ICN1 staining in both the Paneth cell population and the adjacent (non-Paneth) adenoma cells." (PMID 34831152, 2021).
mastitis (12 papers, 2013 to 2025). Inflammation of breast tissue during lactation or postpartum due to an obstructed duct or infection. "However, how LYZ alleviates BMB damage caused by mastitis must be further demonstrated." (PMID 39099401, 2024). "This is one of the regulatory mechanisms of the anti‐mastitis in GED goats with high LYZ expression." (PMID 39099401, 2024). "Upon Escherichia Coli (E. coli) mammary gland infection, GED goats exhibited increased LYZ expression, showing robust anti‐mastitis capabilities, mitigating PANoptosis activation, and alleviating blood‐milk‐barrier (BMB) damage." (PMID 39099401, 2024). "This suggested that high expression of LYZ in GED goats can inhibit PANoptosis activation when mastitis occurs." (PMID 39099401, 2024). "In vivo experiments, we found that the high expression of LYZ in GED goats can alleviate mastitis and BMB damage very well." (PMID 39099401, 2024). "GED goats exhibit an innate capacity for high LYZ expression, thus conferring safe, efficient, and specific anti‐mastitis properties." (PMID 39099401, 2024). "After in vitro application of AgNPs, the anti-lysozyme activity for seven bacteria important for cow mastitis decreased on average by ~11.3%; while, after the application of six antibiotics, in contrast, it increased by 8.2%." (PMID 37175561, 2023). "In the study of isolated bacterial strains from the milk of cows with subclinical mastitis confirmed by the California test, it was found that the index of anti-lysozyme activity of all studied strains was in the interval of 75.2–81.3%." (PMID 37175561, 2023). "In the present work, the influence of the application of six antibiotics from one side and AgNPs from the other side on the adhesive and anti-lysozyme activities of seven bacteria (frequent in cow mastitis) were studied in vitro and in vivo." (PMID 37175561, 2023). "It has been used to control bacteria responsible for mastitis, which requires significant antibiotic therapy, e.g., engineered lysozyme and lysostaphin." (PMID 34900756, 2021). "In 2021, another biological disinfectant preparation for preventing mastitis in dairy cows, which included bactericidal effective amounts of lysostaphin (0.1–10%), lysozyme (1–40%), and other auxiliary components, was patent protected." (PMID 34943746, 2021). "In 2008, a patent application about a topical composition containing lysozyme, serratiopeptidase, Oscimum sanctum, and Azadirechta, for the prevention and/or treatment of mastitis and metritis in mammals, was filed." (PMID 34943746, 2021). "In the present study, the use of lysozyme dimer increased the therapeutic efficiency by 6.7%, compared with the control mastitis group." (PMID 32228579, 2020). "The increased effectiveness of antibiotic therapy combined with lysozyme dimer in mastitis treatment has been observed in cows vaccinated against staphylococcus infections." (PMID 32228579, 2020). "Anaerobic cow mastitis induced by C. perfringens increased lysozyme activity in milk samples, which was positively correlated with disease severity." (PMID 31428367, 2019). "Many genes associated with mastitis, such as the genes of major histocompatibility complex (MHC), β-defensin 5, lactoferrin (LF), lysozyme, and lysostaphin, have been researched and mastitis resistant cDNA library has been constructed." (PMID 27047144, 2015). "Therefore, GED goats with IRS‐targeted integrations into the LYZ promoter region were successfully obtained for the subsequent analysis of mastitis resistance." (PMID 39099401, 2024). "High LYZ expression in GED goats reduced the severity of mastitis and alleviated BMB damage." (PMID 39099401, 2024). "Additionally, our study confirmed the involvement of PANoptosis in BMB damage during mastitis pathogenesis and shed light on the potential regulatory mechanism of LYZ's anti‐inflammatory effect through regulating high mobility group box 1 (HMGB1) expression." (PMID 39099401, 2024).
mastitis (continued). "The utilization of lysozyme as an alternative antibiotic in the veterinary field was explored in several patents and papers, particularly for the treatment/prevention of mastitis and in combination with other substances as antiviral to treat the bovine viral diarrhea virus (BVDV)." (PMID 34943746, 2021). "We may speculate that the LYZ gene in this CNVR may play a role in the immune response to bacterial infections as e.g. the mastitis." (PMID 30261013, 2018). "Milk from transgenic mice containing 0.38 mg/ml recombinant human lysozyme was found to be bacteriostatic against Pseudomonas fragi, Lactobacillus viscous and a mastitis-causing strain of S. aureus, but not against a pathogenic strain of E. coli.." (PMID 23799010, 2013). "Milk from human lysozyme transgenic goats (270±84 μg/ml) is capable of slowing the growth of mastitis-causing strains of E. coli and S. aureus, but does not affect the growth of an organism involved in cheese-making, Lactococcus lacti." (PMID 23799010, 2013). "Upon Escherichia Coli mammary gland infection, GED goats exhibited significantly increased lysozyme expression, mitigation of PANoptosis activation, and alleviation of blood‐milk‐barrier damage, and reduced somatic cell count in milk, indicating robust anti‐mastitis capabilities." (PMID 39099401, 2024). "In addition, the researchers demonstrated a strong anti-mastitis capacity by targeted integration of the gene with a targeted insertion of the innate inflammatory regulatory sequence into the promoter region of the lysozyme gene in dairy goats, which was persistently expressed." (PMID 39714166, 2025). "Upon E. coli mammary gland infection, GED goats exhibited significantly increased LYZ expression, thereby inhibiting the activation of PANoptosis, alleviating BMB damage and reducing the severity of mastitis." (PMID 39099401, 2024). "Different types of supportive medicine, such as antioxidants (vitamin C and E, and β-carotene), lysozyme dimer, or NSAID can be useful in improving fertility in mastitis cows treated with antibiotic only." (PMID 32228579, 2020). "In the absence of mastitis, LYZ expression was no significant changed in the mammary glands of GED goats." (PMID 39099401, 2024). "However, under mastitis conditions, LYZ expression was increased by IRS, thereby reducing the severity of mastitis and showing robust anti‐mastitis capabilities." (PMID 39099401, 2024). "Additionally, our findings suggested that the anti‐inflammatory action of LYZ can be achieved by regulating HMGB1 expression, thereby mitigating the progression of mastitis." (PMID 39099401, 2024). "Therefore, high LYZ expression in GED goats can improve the permeability and integrity of the BMB by inhibiting the activation of PANoptosis and preventing the release of pro‐inflammatory factors, thereby preventing the progression of mastitis." (PMID 39099401, 2024). "Therefore, LYZ can regulate the inflammatory response by down‐regulating the expression of HMGB1 in gene‐edited GMEC, which is one of the regulatory mechanisms of the anti‐mastitis in vivo following high LYZ expression in GED goats." (PMID 39099401, 2024). "Notably, in an in vitro GMEC mastitis model, gene‐edited GEMC with high LYZ expression decreased the expression of key PANoptosis proteins and significantly reduced the rates of apoptosis and cell necrosis, suggesting that LYZ effectively inhibited the activation of PANoptosis." (PMID 39099401, 2024). "We determined that IRS could increase LYZ expression in gene‐edited GMEC and attenuate the inflammatory response; however, further validation is needed to determine whether IRS can increase LYZ expression in individuals and thereby reduce the severity of mastitis." (PMID 39099401, 2024).
periodontitis (12 papers, 2008 to 2025). An acute or chronic inflammatory process that affects the tissues that surround and support the teeth. "Co-expression analysis revealed enrichment in immune and oral health-associated pathways, including salivary protein's role in periodontitis (p=0.007; OR=118.8; LYZ, LTF) and dental caries (p=0.007; OR=59.36; LYZ, CCL28)." (PMID 41552085, 2025). "Saliva contains abundant antibacterial proteins such as lysozyme, and cystatins, but there is only a single report of significantly reduced levels of salivary cystatins in periodontitis and the results from studies of salivary lysozyme have been contradictory." (PMID 24944840, 2014). "Astronauts have been previously shown to exhibit decreased salivary lysozyme and increased dental calculus and gingival inflammation in response to space flight, host factors that could contribute to oral diseases such as caries and periodontitis." (PMID 28649626, 2017). "However, a limitation of this study was the lack of access to oral health clinical records, as elevated IgA levels may reflect both IBD and inflammatory oral lesions, and reduced salivary lysozyme level can also be presented in cases of gingivitis and periodontitis." (PMID 41303678, 2025). "Other strongly associated proteins in this pathway were salivary proteins involved in periodontitis (OR=118.80, adjusted, p=0.007; genes: LYZ, LTF) and proteins involved in dental caries (OR=59.36, p=0.007; genes: LYZ, CCL28)." (PMID 41552085, 2025). "Among these pathways, key pathways relevant to our hypothesis include the role of salivary proteins in periodontitis (OR=118.80, adjusted, p=0.007; genes: LYZ, LTF) and proteins involved in dental caries (OR=59.36, p=0.007; genes: LYZ, CCL28)." (PMID 41552085, 2025).